RAB32 (RAB32, member RAS oncogene family)
Diseases named in the same sentence as RAB32 in open-access papers (continued):
Sharing a sentence is not in itself a finding about the gene and the disease.
glioma (continued). "Univariate analysis showed that RAB32 (HR = 2851, p < 0.001), age (HR = 1.665, p < 0.001), IDH mutation (HR = 0.336, p < 0.001), 1p19q (HR = 0.237, p < 0.001) and the chemotherapy (HR = 0.775, p = 0.011) was a prognostic factor for OS in glioma patients." (PMID 39668831, 2024). "Additionally, RAB32 plays a crucial role in tumor immunity by influencing the malignant progression of glioma and patient survival." (PMID 39668831, 2024). "Further experiments should be conducted to validate the correlation between RAB32 expression and immune infiltration, as well as to investigate whether immunotherapy can effectively inhibit RAB32 expression to improve the prognosis of glioma patients." (PMID 39668831, 2024). "Moreover, glioma patients with high RAB32 expression exhibited higher expressions of immune checkpoint molecules than those with low RAB32 expression." (PMID 39668831, 2024). "Therefore, RAB32 holds promise as both a biomarker and potential therapeutic target for glioma treatment." (PMID 39668831, 2024). "In order to address whether Rab32 plays a role in GBM, we first analyzed the mRNA level of Rab32 in gliomas based on RNA-sequencing from TCGA, CGGA, and Rembrandt public datasets." (PMID 36922509, 2023). "We wondered whether Rab32 regulated mitochondrial dynamics in glioma that contribute to its role in GBM aggressiveness." (PMID 36922509, 2023). "In addition, we evaluated the effect of Rab32 on glioma cell proliferation and apoptosis by clone formation assay as well as the Propidium Iodide-Annexin V assay." (PMID 36922509, 2023). "In the present study, we compared the expression level of Rab32 between normal brain tissues and different subgroups of gliomas based on both cancer public datasets and clinical tissue samples, and found elevated Rab32 expression in GBMs, especially in the most malignant mesenchymal subtype." (PMID 36922509, 2023). "Furthermore, Rab32 expression levels were elevated significantly with the increase of WHO grade of glioma (p < 0.0001)." (PMID 36922509, 2023). "Similarly, multivariate analysis showed that RAB32 (HR = 1.735, p < 0.001), age (HR = 1.528, p < 0.001), IDH mutation (HR = 0.610, p < 0.001), and 1p19q were all absent (HR = 0.381, p < 0.001) and were prognostic factors for OS in glioma patients." (PMID 39668831, 2024). "In addition, univariate and multivariate Cox regression analyses were performed on the CGGA OS data of glioma patients to explore whether RAB32 is an independent prognostic factor of glioma." (PMID 39668831, 2024). "Nevertheless, further investigation is warranted to fully elucidate the precise role of RAB32 in GBM, thereby clarifying its implications for glioma diagnosis and treatment." (PMID 39668831, 2024). "To gain additional insights into the functional role of RAB32 in gliomas, we performed GSEA using the TCGA and CGGA databases to identify significantly activated pathways in patients with high RAB32 expression in GBM as compared to those with low RAB32 expression." (PMID 39668831, 2024). "The results of the survival analysis showed that RAB32 expression in HGG was negatively correlated with glioma survival, the overall survival (OS) time of HGG patients with RAB32 overexpression was shorter, and the results from the two databases were consistent." (PMID 39668831, 2024). "Our bioinformatics analysis revealed a negative correlation between RAB32 expression and DNA methylation in gliomas." (PMID 39668831, 2024). "The role of Rab32 in tumors is poorly explored, with only few studies reporting that Rab32 promotes tumor progression in hepatocellular and ovarian cancers, but no study of Rab32 is performed on glioma." (PMID 36922509, 2023).
multiple sclerosis (3 papers, 2017 to 2025). A progressive autoimmune disorder affecting the central nervous system resulting in demyelination. "RAB32 induces unfolded protein response during multiple sclerosis and experimental autoimmune encephalomyelitis, alters mitochondrial morphology, and promotes apoptosis/necroptosis." (PMID 40250624, 2025). "In fact, in inflammatory demyelinating diseases such as multiple sclerosis and experimental models, the upregulation of Rab32 affects the membranous contacts between the ER and mitochondria in response to ER stress." (PMID 39311306, 2024).
experimental autoimmune encephalomyelitis (2 papers, 2017 to 2025). An autoimmune demyelinating disease of the central nervous system that is produced experimentally in animals by the injection of homogenized brain or spinal cord in Freund's adjuvant. "We assessed Rab32 expression in MS patient and experimental autoimmune encephalomyelitis (EAE) tissue, via observation of mitochondria in primary neurons and via monitoring of survival of neuronal cells upon increased Rab32 expression." (PMID 28115010, 2017).
hepatocellular carcinoma (2 papers, 2021 to 2023). A malignant tumor that arises from hepatocytes. "Rab32 knockdown increases lysosome biogenesis in hepatocellular carcinoma and cervical cancer and reduces the association of mTOR pathway proteins with lysosomes, which suggests that Rab32 regulates lysosomal mTORC1 trafficking and thereby controls metabolism." (PMID 34141705, 2021). "A recent study showed that Rab32 serves as an oncogene in hepatocellular carcinoma with the potential to promote the growth and invasion of tumor cells, while a higher level of Rab32 was strongly related to the advanced tumor stage and poor survival in patients with hepatocellular carcinoma." (PMID 36922509, 2023).
lung carcinoma (2 papers, 2020 to 2021). "This time, differently from what we measured with Rab27a silencing, Rab32 knockdown was crucial for the observed miR-124a effect on EV release in lung cancer cell lines." (PMID 32974168, 2020). "We then sought to comprehensively examine the respective roles of miR-124a, Rab27a, and Rab32 on EV release in lung cancer." (PMID 32974168, 2020). "It has been reported that Rab32 is involved in post-Golgi trafficking and was considered to be a good candidate for regulating EV release in our lung cancer model." (PMID 32974168, 2020). "To examine the effect of Rab32 targeting on EV release, we decreased Rab32 expression by both siRNA and miR-124a overexpression in the H1299 lung cancer cell line." (PMID 32974168, 2020). "We combined the downregulation of both Rab-27 and Rab32 (siRNAs) with miR-124a overexpression, and then measured the total EVs and exosomes released, in the H1299 lung cancer cell line." (PMID 32974168, 2020). "To assess the biological role of Rab32 on EV release and its relationship with miR-124a in lung cancer, we silenced Rab32 and overexpressed miR-124a in a NSLC adenocarcinoma cell line similarly as we did with Rab27a." (PMID 32974168, 2020). "Here, we investigated the relationship between miR-124a, Rab32, and their impact on EV release in lung cancer cell lines." (PMID 32974168, 2020).
neuroblastoma (2 papers, 2017 to 2018). Neuroblastoma (NB) is the most common solid, extracranial childhood tumor. "The treatment of human neuroblastoma SH-SY5Y cells with ER stress inducers leads to transcriptional activation of Rab32, indicating that the expression of Rab32 may be under the control of the ER stress-induced UPR." (PMID 30340324, 2018). "We repeated this survival assay using human SH-SY5Y neuroblastoma cells and found these cells to be even more dependent on Rab32, regardless of whether it was active or inactive." (PMID 28115010, 2017).
oculocutaneous albinism type 7 (2 papers, 2025). Oculocutaneous albinism type 7 (OCA7), formerly called OCA5, is a form of oculocutaneous albinism (OCA) characterized by skin and hair hypopigmentation, nystagmus and iris transillumination. "We reveal how LRMDA mutations, causative for oculocutaneous albinism type 7 (OCA7), a hypopigmentation disorder accompanied by poor visual acuity, uncouple RAB32 and Commander binding thereby establishing the mechanistic basis of this disease." (PMID 39975051, 2025).
peripheral nerve injury (2 papers, 2024). Injury to a peripheral nerve. "Rab32 can be a potential target for future therapeutic strategy in the treatment of peripheral nerve injuries." (PMID 38388913, 2024). "In this study, our research confirms that Rab32 plays a pivotal role in peripheral nerve injury (PNI), exacerbating PNI-induced Schwann cell pyroptosis and enhancing inflammatory response." (PMID 38388913, 2024).
acute myeloid leukemia (1 paper, 2024). Acute myeloid leukemia (AML) is a group of neoplasms arising from precursor cells committed to the myeloid cell-line differentiation. "The findings showcased the significance of RAB32 in multiple cancer types, including but not limited to bladder urothelial carcinoma (BLCA), acute myeloid leukemia (LAML), LGG, and pancreatic adenocarcinoma (PAAD)." (PMID 39668831, 2024).
autism (1 paper, 2016). Persistent deficits in social interaction and communication and interaction as well as a markedly restricted repertoire of activity and interest as well as repetitive patterns of behavior. "In more detail, we found one Rab32 always coupled with the melanoma oncogene Grm1, while one Rab38 is always close to Grm5, a gene playing a fundamental role in many human disorders such as schizophrenia and autism." (PMID 26818140, 2016).
brain inflammation (1 paper, 2017). "Supporting the idea that Rab20, together with Rab32, are part of a group of small GTPases linked to inflammation, the up-regulation of both Rab20 and Rab32 during the acute phase of LPS-induced brain inflammation has been reported." (PMID 29034219, 2017).
cholangiocarcinoma (1 paper, 2024). A carcinoma that arises from the intrahepatic biliary tree (intrahepatic cholangiocarcinoma) or from the junction, or adjacent to the junction, of the right and left hepatic ducts (hilar cholangiocarcinoma). "Our analysis of RAB32 expression across various cancers and their corresponding normal tissues, utilizing the TIMER2.0 database, revealed a notable increase in RAB32 expression levels in diverse types of cancers such as cholangiocarcinoma (CHOL), GBM, and renal clear cell carcinoma (KIRC)." (PMID 39668831, 2024).
colitis (1 paper, 2018). Inflammation of the colon. "We found that Rab32 deficiency in CD11c+ cells exacerbates the progression of colitis in mice with increased neutrophil infiltration and bacterial invasion." (PMID 30338217, 2018). "To investigate the roles of Rab32 in CD11c+ cells in DSS‐induced colitis, we generated CD11c+ cell‐specific Rab32‐deficient (CD11c‐Cre+Rab32f/f) mice." (PMID 30338217, 2018). "In this study, we found that Rab32 deficiency in CD11c+ cells aggravates the progression of DSS‐induced colitis, with a more severe inflammation appearance, colonic tissue damages and higher mortalities." (PMID 30338217, 2018). "Our data support the hypothesis because Rab32 deficiency in CD11c+ cells resulted in a more severe colitis progression and increased the frequency of CD11b+Ly6G+ neutrophils in inflamed tissue." (PMID 30338217, 2018). "The present data demonstrate that Rab32 knockout in CD11c+ cells aggravates the development of DSS‐induced colitis and suggest that the Rab32‐related antimicrobial pathway is involved in the pathogenesis of IBD." (PMID 30338217, 2018). "In this study, we examined the role of Rab32 in a dextran sodium sulfate (DSS)‐induced colitis model." (PMID 30338217, 2018). "The data indicate the Rab32‐related antimicrobial pathway is involved in the progress of colitis." (PMID 30338217, 2018). "To determine the role of Rab32 in the pathogenesis of IBD, we administered dextran sodium sulfate (DSS) to CD11c+ cell‐specific Rab32 knockout (CD11c‐Cre+Rab32f/f) mice to induce colitis." (PMID 30338217, 2018).
COVID-19 (1 paper, 2024). A disease caused by infection with severe acute respiratory syndrome coronavirus 2. "Our work highlighted an increased expression of genes related to the endomembrane system, such as RAB1B, RAB24, RAB32, JAK3, and SELP, in severe COVID-19 patients’ blood samples." (PMID 38262689, 2024).
endometrial cancer (1 paper, 2015). Primary or metastatic malignant neoplasm involving the endometrium (mucous membrane that lines the endometrial cavity). "Indeed, hypermethylation of RAB32 has been identified in gastric and endometrial cancer." (PMID 25807146, 2015).
HIV-1 infection (1 paper, 2015). The type species of lentivirus and the etiologic agent of acquired immunodeficiency syndrome (AIDS). "The fact that seven CpGs associated with RAB32 show increased methylation strongly suggests that expression of this gene is suppressed in response to aging and HIV-1 infection." (PMID 25807146, 2015).
Listeria infection (1 paper, 2017). "Rab38 and its close homolog Rab32 were also reported to control Salmonella and Listeria infection." (PMID 29034219, 2017). "Furthermore, high throughput siRNA screening to identify host pathways during L. monocytogenes infection in HeLa cells demonstrated that both Rab20 and Rab32 are required for the control of Listeria infection." (PMID 29034219, 2017).
lung adenocarcinoma (1 paper, 2022). A carcinoma that arises from the lung and is characterized by the presence of malignant glandular epithelial cells. "We further examined co-expression of RAB32 and THBS1 in lung adenocarcinoma cases from the cancer genome atlas (TCGA, Firehose legacy, 586 samples) and found that mRNA levels of RAB32 and THBS1 positively correlated with each other." (PMID 35884490, 2022).
Lung fibrosis (1 paper, 2022). "Lung fibrosis is the leading cause of death among adults with HPS-1 and HPS-4 genetic types, which are associated with defects in the biogenesis of lysosome-related organelles complex-3 (BLOC-3), a guanine exchange factor (GEF) for a small GTPase, Rab32." (PMID 35739508, 2022).
malaria (1 paper, 2012). Malaria is a serious and sometimes fatal disease caused by a parasite that commonly infects a certain type of mosquito which feeds on humans. "The results showed that, compared to the negative control, the live malaria parasite was able to induce an increase in the expression of Rab1a, Rab1b, Rab7a, Rab10, Rab14, Rab20, Rab27a, Rab32 and Rab38." (PMID 22911692, 2012).
osteoporosis (1 paper, 2023). A condition of reduced bone mass, with decreased cortical thickness and a decrease in the number and size of the trabeculae of cancellous bone (but normal chemical composition), resulting in increased fracture incidence. "Our results indicate that both Rab32 and Rab38 may serve as drug targets for suppressing osteoclast function and may be developed like a bisphosphonate or like odanacatib, a CTSK inhibitor, as a therapeutic agent for rheumatoid arthritis, osteoporosis, and periodontitis." (PMID 37793839, 2023).
infection (17 papers, 2012 to 2026). The state of being infected such as from the introduction of a foreign agent such as serum, vaccine, antigenic substance or organism. "Other studies have demonstrated that Rab32 is also recruited to Salmonella Typhi‐containing vacuoles and that Rab32‐ or HPS4‐deficient mice are more susceptible to infection by the pathogen than wild‐type mice are." (PMID 32542850, 2021). "Shortly after infection, Rab32 was recruited to the B. pseudomallei–containing phagosomes and remained associated with these phagosomes for several hours after infection." (PMID 31199852, 2019). "While the direct transcriptional regulation of Rab32 in response to cytokines is unclear, some reports have directly linked Rab32 to immune responses in animal models of infection." (PMID 29034219, 2017). "Rab32 is associated with vesicle remodeling and plays an important role in mediating antimicrobial activity by promoting phagosome maturation at an early phase of infection." (PMID 33946162, 2021). "It would also be beneficial to understand whether the kinase activity of LRRK2 during the infection is associated with Rab32 and plays a pivotal role in the defense mechanism of the host against Salmonella." (PMID 33426511, 2021). "The enrichment analysis based on the DisGeNET database revealed a relationship between RAB32 and infection." (PMID 38448858, 2024). "Upon infection, RAB32 interacts with the mitochondrial immunoresponsive gene 1 (IRG1) product aconitate decarboxylase 1 (ACOD1) and facilitates the delivery of itaconic acid to the pathogen-containing vacuole to inhibit bacterial growth." (PMID 38293014, 2024). "One of the identified SNARE trafficking proteins, Rab32, was highly synthesized by macrophages during the indirect infection." (PMID 33946162, 2021). "There was a gradual increase over time in the ratio of Rab32 to β-actin in B. pseudomallei infection (multiplicity of infection, MOI = 10:1) as compared with an uninfected control in RAW264.7 cells." (PMID 31199852, 2019). "Here, we showed that the host Rab32 plays an important role in mediating antimicrobial activity by promoting phagosome maturation at an early phase of infection with B. pseudomallei." (PMID 31199852, 2019). "We found that enhanced green fluorescent protein (EGFP)-Rab32 was strongly recruited to the B. pseudomallei-containing phagosomes 1 h to 6 h post-infection (p.i.)i.e., after bacterial internalization." (PMID 31199852, 2019). "Taken together, these results indicated that a substantial fraction of Rab32-positive phagosomes harboring B. pseudomallei appears to fuse with acidic late endosomes at early stages of infection." (PMID 31199852, 2019). "Here, we demonstrate that Rab32 is involved in host defense against B. pseudomallei in the early stages of infection by regulating phagosome maturation in macrophages." (PMID 31199852, 2019). "In this study, we determined that the infection of macrophages with B. pseudomallei resulted in the upregulation of Rab32 expression through the inhibition of miR-30b/30c expression." (PMID 31199852, 2019). "It will be interesting to investigate how the GtgE-processed Rab32 contributes further to the infection process." (PMID 29298974, 2018). "During infection, the Salmonella Rab32-GAP SopD2 is released and catalyzes the conversion of Rab32:GTP to Rab32:GDP15." (PMID 29298974, 2018). "In order to stably establish the infection, Salmonella counteracts Rab32-dependent membrane pathways with SopD2 and GtgE, leading to Rab32 conversion into the GDP-state and irreversible proteolysis in the switch I region, respectively." (PMID 29298974, 2018). "Rab32 has also been shown to control infection by Listeria monocytogenes, another medically relevant intracellular pathogen." (PMID 27645564, 2018).